IGF1 (insulin like growth factor 1)
Diseases named in the same sentence as IGF1 in open-access papers (continued):
Sharing a sentence is not in itself a finding about the gene and the disease.
injury (30 papers, 2012 to 2026). Damage inflicted on the body as the direct or indirect result of an external force, with or without disruption of structural continuity. "BAL levels of CXCL1, CXCL2, IL-1β, TNFα and TGFβ were increased during the early phase, while IGF-1 levels were significantly increased in the later phase, suggesting that IGF-1 is involved in the resolution processes of acute lung injury." (PMID 41431237, 2026). "It seems that increased IGF-1 correlates positively with all progenitor cell lines on the same or the subsequent days, while perinatal stress and brain injury correlate with low IGF-1 levels in the following days." (PMID 40149963, 2025). "The neurogenic effects of IGF1 were confirmed using a continuous intracerebroventricular infusion of IGF1 to mice after CCI brain injury, resulting in significantly improved recovery of the immature neuron population within the DG." (PMID 34095131, 2021). "The insulin‐like growth factor 1 (IGF‐1) receptor is activated either by Igf1 or by Igf2 and is neuroprotective following brain injury." (PMID 28961383, 2017). "In a comparative multiplex analysis, MSC-CM attenuated lung inflammation and promoted an anti-inflammatory M2 macrophage phenotype via insulin-like growth factor 1 (IGF-1) secretion in LPS-induced lung injury." (PMID 29254275, 2017). "Chronic alcohol abuse is known to decrease IGF-1 production due to ethanol-induced liver injury, but again it is unlikely that our participants were liver injured or chronic alcohol abusers." (PMID 25946190, 2015). "Notably, although inhibition of IGF-1/IGF-1R signalling has different effects in a phase-dependent manner during the course of acute lung injury, IGF-1 stimulation consistently improves the conditions from the acute phase to the recovery phase." (PMID 41431237, 2026). "Next, we explored whether exogenous IGF-1 can ameliorate brain damage using a neonatal mouse HI brain injury model." (PMID 41256775, 2025). "IGF-1 has a constructive significance for normal brain growth and development, and may play a role in protection and repair after brain injury." (PMID 41256775, 2025). "IGF-1 has been shown to exert its neuroprotective effects on different cells after brain injury." (PMID 31338023, 2019). "In rodents, intranasal IGF‐1 has been shown to rapidly and effectively gain entry to the CNS via the olfactory and trigeminal system, and protect against Huntington disease and toxin‐induced brain injury." (PMID 26534869, 2016). "In a traumatic brain injury (TBI) rat model, IGF-1 is shown to increase in the ipsilateral side of the brain injury." (PMID 31338023, 2019). "Furthermore, insulin-like growth factor-1 (IGF-1) and neurotrophic growth factor (NGF) have also been validated for their neuroprotective effects in cases of retinal injury." (PMID 38585147, 2024). "If astrocyte-derived IGF-1 is neuroprotective in the cortex, this could contribute to improved motor function in IGF-1Tg mice after brain injury, as early impairment in motor function after TBI has been correlated with the volume of cortical injury." (PMID 23826235, 2013). "Additionally, IGF-1 exhibits antiapoptotic and mitogenic characteristics, which may explain the protective effect of IGF-1 against potential kidney injury in preterm pigs." (PMID 38762663, 2024).
liver cancer (30 papers, 2008 to 2025). An epithelial or non-epithelial malignant neoplasm that arises from the liver. "The alterations in insulin-like growth factor-1 and its receptor axis have been reported to contribute to the pathogenesis of liver cancer." (PMID 39125385, 2024). "There was elevated nuclear expression of IRS4 in liver cancer and treatment of HEPG2 cell, a liver cancer cell line with IGF-1 and EGF-induced nuclear translocation of IRS4, stimulating cell proliferation by a β-catenin/Rb/cyclin D mechanism." (PMID 37686244, 2023). "It has also been found that in liver cancer, IGF-1 promotes the invasion and metastasis of liver cancer cells by inhibiting the degradation of cathepsin B." (PMID 34804946, 2021). "Dysregulation of EGF, HGF, and IGF-1 plays a crucial role in the development of hepatic cancer and metastases." (PMID 34572344, 2021). "Serum IGF-1 levels have been suggested to be predictors of progression and survival in liver cancer patients." (PMID 34572344, 2021). "IGFBP-1, which is expressed in the liver and binds IGF-1, is regulated by HIF1α in HepsG2, a human liver cancer cell line." (PMID 32610471, 2020). "Longitudinal observation of liver cirrhotic patients showed a decrease in IGF1 concentration in those who developed primary liver cancer." (PMID 29702590, 2018). "Some case–control studies have supported a positive association between the insulin-like growth factor-1 (IGFI) level and the risk of liver cancer." (PMID 29113370, 2017). "The IGF1 to IGFBP3 molar ratio represents the level of active IGF1, and patients with an IGF1 concentration higher than their IGFBP3 level are at an increased risk of liver cancer." (PMID 29113370, 2017). "In these studies, EGCG causes a decrease in the expression levels of IGF-1/2, but an increase in the expression levels of IGFBP-3, which negatively controls the expression of IGF-1/2, in colon and liver cancer cells." (PMID 19325845, 2008). "IGF1 regulates cell proliferation by activating the downstream cell signal regulatory protein serine/threonine kinase Akt, and its main receptor IGF1‐R is also increased in liver cancer." (PMID 35421276, 2022). "Therefore, we aimed to explore the relationship between lncRNA TUG1, miR‐1‐3p and IGF1 and their influence mechanism on the proliferation and apoptosis of liver cells to provide new insights into the prevention and treatment of liver cancer." (PMID 35421276, 2022). "IGF1 was noted to play a crucial role in metastasis and tumor growth of liver cancer." (PMID 34707090, 2021). "IGF-1 is a crucial gene in liver cancer, and is highly up-regulated in HCC." (PMID 34572344, 2021). "On the contrary, the IGF1/IGFBP3 ratio decreased in patients with liver cancer." (PMID 29702590, 2018). "Previous studies have found that abnormal levels of IGF-1 in malignant tumors, including breast, lung, prostate and liver cancers, may be correlated with autocrine IGF-1 expression." (PMID 25663870, 2015). "In addition, the development and progression of liver cancer and liver metastases is a multifactorial process, linked to alterations in some prominent cellular signaling pathways, including dysregulation of HGF, EGF, and IGF-1." (PMID 34572344, 2021). "HCC patients of Child–Pugh class C (p = 0.002), Barcelona Clinic Liver Cancer Stage-B (BCLC-B) (p < 0.01), or BCLC-C (p = 0.019) had significantly lower baseline IGF1 levels." (PMID 29113370, 2017).
Osteopenia (29 papers, 2009 to 2025). Osteopenia is a term to define bone density that is not normal but also not as low as osteoporosis. "Second, further studies using skeletal muscle-specific IGF-1-deficient mice are necessary to precisely clarify the role of muscle-derived IGF-1 in hyponatremia-induced osteopenia in mice." (PMID 40227313, 2025). "Although there are similarities in some phenotypes, the osteosclerotic bone phenotype in the Csf1rko is quite distinct from osteopenia associated with GH or IGF1 deficiency." (PMID 34081701, 2021). "There are some reports that elaborated that IGF-1 is associated with an increase in the muscle mass and muscle fiber area, even inhibiting osteopenia." (PMID 34443530, 2021). "It was shown also that osteopenia was associated with low serum IGF-1 levels and bone formation markers." (PMID 21772974, 2011). "Moreover, low levels of IGF-1 were found to be associated with osteopenia in type 1 DM patients." (PMID 21772974, 2011). "Alendronate, dehydroepiandrosterone (DHEA), and insulin-like growth factor-1 (IGF-1) are among the more recent medicinal alternatives for the treatment of osteopenia." (PMID 38770510, 2024). "IGF-1 stimulates osteoblast proliferation as well as osteoclast differentiation to inhibit osteopenia." (PMID 19527531, 2009). "Additionally, the decreased serum IGF-1 level in diabetic patients may contribute to the development of osteopenia." (PMID 30459613, 2018). "Whilst the osteopenia observed in osteoblast-specific Gab1 knockout mice has been linked to impaired IGF-1/insulin signaling via both PI3K and Ras pathways, recent data suggests the mitogenic effect of IGF-1 requires both pathways, whilst differentiation relies on PI3K/AKT signaling." (PMID 22833734, 2012). "One of the most recent found no impact on IGF-1 in women with osteopenia after a 24-month intervention, which is consistent with other studies reporting that isoflavone supplementation did not alter the IGF system." (PMID 32824177, 2020). "Here, we reported that the serum levels of insulin, c-peptide and IGF-1 were lower in diabetic untreated animals that control non-diabetic ones, which suggest the enrolment of insulin/IGF-1 in diabetic osteopenia." (PMID 34371877, 2021).
preeclampsia (29 papers, 2007 to 2025). Preeclampsia is a hypertensive disorder of pregnancy that is characterized by new-onset hypertension with proteinuria presenting after 20 weeks of gestation, and depending on mild or severe forms may initially present with severe headache, visual disturbances, and hyperreflexia. "It is well established that maternal IGF-1 has important growth effects on the foetus and myometrial vasculature, which are relevant processes to the cause of preeclampsia." (PMID 26213997, 2015). "The combination of preeclampsia presenting with severe FGR at earlier gestational ages may share a common cellular pathophysiologic pathway through deficiency of IGF-1, which is in turn associated with reduced VEGF." (PMID 39337133, 2024). "Similar to its pro-angiogenic effects in placental gene transfer in FGR, we speculate that placental gene therapy with IGF-1 may address the underlying vascular endothelial cell dysfunction in preeclampsia." (PMID 39337133, 2024). "In addition, the expression OPG is the same as other hormones, such as Leptin, IGF-1 and adiponectin/receptor, which are associated with the pathogenesis of preeclampsia." (PMID 22952959, 2012). "In patients with preeclampsia, the IGF-1 (insulin-like growth factor 1) expression was significantly reduced compared with healthy pregnancy, associated with a downregulation of ZEB1." (PMID 41463130, 2025). "In vitro BeWo cell culture and treatment with TNF-α and IGF-1 supports studies on different inflammatory conditions including preeclampsia." (PMID 41155321, 2025). "Many studies have reported lower serum IGF-1 (insulin-like growth factor 1) levels in women with preeclampsia as well as lower placental expression of IGF-1." (PMID 28822014, 2017). "Paradoxically, the only study that has looked at IGF-1 protein levels in the circulation showed an increased level of IGF-1 in the first and second trimester of pregnancy in preeclampsia." (PMID 26213997, 2015). "In parallel, IGF-1, a target gene of miR-206, was also found to be downregulated (0.41 ± 0.04) in placental tissue from women with preeclampsia." (PMID 26213997, 2015). "Placental IGF-1 mRNA expression was downregulated in placental tissue in preeclampsia in the present study." (PMID 26213997, 2015). "However, other studies have shown low IGF-1 expression in women with preeclampsia compared to women in normal pregnancy." (PMID 41463130, 2025). "One study showed that IGF-1 may inhibit the development of preeclampsia by decreasing miR-183 expression by increasing ZEB1 expression." (PMID 41463130, 2025). "Our study showed increased IGF-1 production by B cells in preeclampsia." (PMID 41463130, 2025). "Our systems and network biology approach revealed several biological pathways, including IGF‐1, that may play a role in the early pathophysiology of preeclampsia." (PMID 37905457, 2023). "The deficiency of IGF-1 could cause harm to the foetus; in fact, Halhali and co-authors have shown that, in women suffering from preeclampsia, there is a decrease in IGF-1 levels also in the cord blood, influencing the growth of the foetus." (PMID 36292666, 2022). "Plasma IGF-1 levels are known to correlate with the severity of preeclampsia." (PMID 36292666, 2022). "The effects of preeclampsia on weight trajectories in boys could be influenced by some of the same mechanisms as those for linear growth, such as low levels of IGF-1, mediated through prematurity and inflammation." (PMID 34682697, 2021). "Indeed, a number of genes regulated in this array were previously found to be associated with pregnancy complications such as preeclampsia (MR, CCL2, IGF-1, secreted phosphoprotein (SPP)-1, MMP-9), preterm labour (CCL18) and intrauterine growth restriction (IGF-1)." (PMID 18446208, 2008). "TGFβ-1, VEGF, IGF-1, and HTRA-1 are unique in that they have all been postulated to play a role in ROP and preeclampsia and have a direct and indirect role in angiogenesis." (PMID 33281553, 2020).
preeclampsia (continued). "Early in life, IGF-1 levels were lower in infants born before 29 weeks of gestation and SGA infants (P < 0.001 and < 0.01, respectively), and tended to be lower in infants born following preeclampsia (P = 0.08)." (PMID 37648745, 2024). "Notably, it has experimentally validated interactions with a number of genes known to be directly involved in the pathology of preeclampsia, particularly at the placenta: VEGF, NOTCH-3, IGF-1 and hypoxia inducible factor 1 α (HIF-1α)." (PMID 26213997, 2015). "We found a statistically significant difference in average infant systemic HTRA-1, but not TGFβ-1, IGF-1, or VEGF-A relative to the presence or absence of ROP and maternal preeclampsia." (PMID 33281553, 2020). "IGF-1 and HTRA-1 demonstrated significantly lower levels of systemic expression in women with early-onset preeclampsia vs. women without preeclampsia." (PMID 33281553, 2020). "Herein we show that HTRA-1, but not TGFβ-1, VEGF, or IGF-1, may mediate ROP protection in the setting of early-onset preeclampsia." (PMID 33281553, 2020).
renal failure (29 papers, 2009 to 2025). "Higher pre-transplant IGF-1 levels, combined with a lower donor kidney dose, were associated with increased risks of kidney failure, excess proteins in the urine, and transplant rejection." (PMID 40327402, 2025). "Such disorders include decreased serum IGF-1 levels, kidney failure as indicated by the increased blood creatinine levels, and increased blood FGF-23 levels." (PMID 31791247, 2019). "Further studies showed that this failure of PTH to maintain blood 1,25(OH)2D levels was associated with decreased blood levels of IGF-1, increased blood levels of FGF-23, and kidney failure." (PMID 31791247, 2019). "A clinical question arising from this work is why the single remaining kidney in the living kidney donor does not experience higher kidney failure risk due to the GH/IGF-1 axis effect." (PMID 40327402, 2025). "BM-MSC improves renal insufficiency by local release of insulin-like growth factor 1 (IGF-1)." (PMID 34239869, 2021). "Consequently, the decreased blood levels of IGF-1, increased blood levels of FGF-23, and kidney failure cause suppressed activity of kidney 1α-hydroxylase, leading to reduced production of 1,25(OH)2D in kidney and decreased 1,25(OH)2D levels in blood." (PMID 31791247, 2019).
Abdominal obesity (27 papers, 2009 to 2025). Excessive fat around the stomach and abdomen. "At the same time, abdominal obesity is associated with several hormonal imbalances, including leptin, insulin-like growth factor (IGF-1), and abnormalities in sex hormone binding globulin (SHBG)." (PMID 40129671, 2025). "Lower levels of insulin-like growth factor-1 in association with abdominal obesity could thus potentially underlie inverse associations of the A:G ratio with %DBV and ADBV." (PMID 22800711, 2012). "In this study, the serum IGF-1 concentration was increased in patients with esophageal adenocarcinoma and EC patients with visceral obesity, suggesting that visceral and abdominal obesity might influence the progression of esophageal adenocarcinoma in association with IGF-1 levels." (PMID 33513939, 2021). "This elucidates the impact of abdominal obesity on IGF-1 levels and the subsequent disruption in glycemic control." (PMID 38285303, 2024). "Adipocytes, particularly in abdominal obesity, can produce hormones and growth factors, such as insulin and insulin-like growth factor-1 (IGF-1), in excess." (PMID 39766104, 2024). "Plasma IGF-1 levels are known to be inversely correlated with BMI particularly in individuals with central obesity." (PMID 32655494, 2020). "Moreover, IGF-1 signalling is known to be dysregulated by both toxin-induced inflammation and central obesity, consistent with our model identifying prospective biomarkers predictive of greater PD risk in these categories." (PMID 37159450, 2023). "Obese individuals, especially those with abdominal obesity, often have increased levels of insulin and insulin-like growth factor-1 (IGF-1), which may promote the development of SIC, as has been hypothesized for other gastrointestinal tumors." (PMID 27294726, 2016). "Abdominal obesity mainly involves the accumulation of VAT, which induces metabolic alterations, including alterations in the levels of insulin-like growth factor 1 (IGF-1) and adipokines such as leptin." (PMID 33513939, 2021). "Our observations allow us to conclude that lower T most affects the abdominal obesity but DHEA and IGF-1 also are involved in body composition rearrangement in patients with PD." (PMID 27274996, 2016).